NUAK1 (NUAK family kinase 1)
Diseases named in the same sentence as NUAK1 in open-access papers (continued):
Sharing a sentence is not in itself a finding about the gene and the disease.
tumor (60 papers, 2010 to 2025). "Overexpression of NUAK1 has been detected in a variety of tumors and is associated with tumor progression." (PMID 39901136, 2025). "Unsurprisingly, these genes have been previously associated with tumor growth and metastasis (NUAK1, TGFBR3, FGFBP2), as well as autoimmune disorders (PRSS23)." (PMID 37066364, 2023). "These genes have been previously associated with tumor growth and metastasis (NUAK1, TGFBR3, FGFBP2), as well as autoimmune disorders (PRSS23)." (PMID 38042785, 2023). "It has been suggested that NUAK1 was strongly associated with tumor invasion and migration, and also played an important role in tumor survival and progression." (PMID 33750398, 2021). "In a xenograft model of intraperitoneal metastasis, NUAK1 loss extended survival and reduced fibronectin expression in tumours." (PMID 32429240, 2020). "According to its association with cancer, NUAK1 plays a role in several processes related to tumor progression, including cell migration, invasion, and metastasis." (PMID 32754444, 2020). "NUAK1 shows stage-dependent expression in cancer tissues and associates with tumor malignancy and poor patient prognosis." (PMID 32754444, 2020). "The identified roles of NUAK1 in cancer metabolism provide a potential mechanism relevant for tumor progression and its association with poor patient prognosis in several cancers." (PMID 32754444, 2020). "Additionally, high NUAK1 expression was positively associated with tumor tissue invasion, lymph node metastasis, poor pathological TNM stage and poor outcomes of patients with ESCC." (PMID 37919754, 2023). "Likewise, colon tumors, which express high MYC levels because of loss-of-function mutations in the APC tumor suppressor gene, depend on NUAK1 for tumor growth and maintenance." (PMID 32006464, 2020). "Furthermore, NUAK1 loss in a xenograft model of intraperitoneal metastasis extended host survival and reduced fibronectin expression in tumours." (PMID 32429240, 2020). "Further studies could shed light on the molecular mechanisms associated with the identified metabolic NUAK1 functions and their implications on cancer cell metabolic adaptation during tumor progression." (PMID 32754444, 2020). "Lastly, we assessed the association between NUAK1 and fibronectin expression in patient tumours." (PMID 32429240, 2020). "By measuring the tumor volume and weight, we found that NUAK1 overexpression dramatically promoted tumor growth in vivo, while knockdown of NUAK1 showed opposite effects on tumor growth." (PMID 39901136, 2025). "Subsequently, we conducted IHC staining to examine the effects of NUAK1 on intratumoral CD8+ T cell infiltration in tumor-bearing mice." (PMID 39901136, 2025). "IHC analyses of tumor tissues from 20 HCC patients suggested that the levels of β-catenin were positively correlated with NUAK1 expression." (PMID 39901136, 2025). "Next, we constructed a subcutaneous xenograft tumor model using NUAK1-overexpression and NUAK1-silencing H22 cells to evaluate the role of NUAK1 in HCC." (PMID 39901136, 2025). "Kaplan-Meier Plotter assay showed that NUAK1 overexpression significantly shortened the OS of tumor-bearing mice, whereas NUAK1 knockdown exhibited opposite effects." (PMID 39901136, 2025). "In the present study, we aimed to investigate the role of NUAK1 in tumor immune microenvironment and explore its potential mechanism in HCC." (PMID 39901136, 2025). "NUAK1 was reported to promote tumor growth and metastasis through inducing cytoskeleton rearrangement and matrix metalloproteinase (MMP) activation in cancer cells." (PMID 39901136, 2025).
tumor (continued). "NUAK1 expression was negatively correlated with CD8+ T cell infiltration in tumor tissues from HCC patients and mice xenograft model." (PMID 39901136, 2025). "Tumor patients with high expression of NUAK1 often have poor prognosis and reduced overall survival." (PMID 39901136, 2025). "IHC analyses of tumor tissues from 20 HCC patients suggested that the levels of p-GSK3β were positively correlated with NUAK1 expression." (PMID 39901136, 2025). "The outcomes indicated that the expression of NUAK1 was dramatically elevated in tumor tissues, and the over-all survival (OS) of patients with high NUAK1 expression was significantly lower than that of patients with low NUAK1 expression." (PMID 39901136, 2025). "In contrast, the deletion of NUAK1 resulted in a significant increase in the population of GZMB+ CD8+ T cells in the tumor region." (PMID 39901136, 2025). "For instance, our study showed that the overexpression of NUAK1, LRRC17, FOXM1, and CDC20 as well as the downregulation of FLRT2 are associated with DNA repair pathway as well as tumor invasion pathways." (PMID 39149564, 2024). "Like Akt, NUAK1 promotes tumor initiation and progression through regulation of cell proliferation, induction of cancer cell survival, cell migration, changes in cellular metabolism, and oxidative stress regulation." (PMID 38135881, 2023). "Considering that ectopic expression of NAUAK1 significantly enhanced the migration and invasion of ESCC cells in vitro, we then determined to further analyze the effect of NUAK1 overexpression on tumor metastasis in vivo." (PMID 37919754, 2023). "NUAK1 a protein kinase of the AMPK family is identified to be involved in the regulation of a variety of genes that regulate tumor invasion and metastasis." (PMID 37576402, 2023). "The high NUAK1 expression positively correlated with tumor stage, invasiveness, poor differentiation, lymph node metastasis and the reduced overall survival of cancer patients." (PMID 37919754, 2023). "Adopting in vitro and in vivo settings, we showed that knocking down NUAK1 promoted the cell migration ability of GC cell line, was correlated to a decrease in tumor growth and rise on ROS content, while miR-622 tended to counteract the activities of NUAK1." (PMID 35872695, 2022). "In terms of phenotype, the growth rate of tumor volume and weight in the NUAK1-shRNA group decreased in comparison with the NC-shRNA group (P < 0.001)." (PMID 35872695, 2022). "Our study also revealed that elevated miR-1182 and let-7a down-regulated NUAK1 expression, resulted in the further inhibition of cell migration, invasion, proliferation as well as tumor growth and promoted autophagy." (PMID 33750398, 2021). "MRT68921 was also shown to be a potent inhibitor of NUAK1 (NUAK family SNF1-like kinase 1) which is a critical component of the antioxidant defence necessary for the survival of tumour cells during cytotoxic therapy and EMT." (PMID 34706732, 2021). "Pharmacologic inhibition with highly specific NUAK1 inhibitors (HTH-01-015 or WZ4003) reduced the ability of these tumors to form spheroids with a tumor-initiating capacity." (PMID 34685740, 2021). "Based on these results, it can be concluded that miR-1182 and let-7a have tumor suppressive effects on CCA via NUAK1 suppression." (PMID 33750398, 2021). "NUAK1 is an AMPK-related kinase located in the cytosol and the nucleus, whose expression associates with tumor malignancy and poor patient prognosis in several cancers." (PMID 32754444, 2020). "We also observed elevated NUAK1 expression in different tumor types, while the expression of NUAK1 was slight in normal cell lines." (PMID 32873786, 2020). "In MYC-overexpressing tumours, NUAK1 reduces metabolic stress by inhibiting mTORC1 and sustaining glutamine metabolism." (PMID 32429240, 2020). "We assessed fibronectin directly in tumour xenografts since our in vitro results indicated that NUAK1 promotes spheroid formation through fibronectin expression and deposition." (PMID 32429240, 2020).
tumor (continued). "Deregulated expression of MYC overrides this control, providing a mechanistic model why tumor cells with high MYC levels depend on NUAK1." (PMID 32006464, 2020). "We found that low NUAK1 expression levels significantly correlates with better prognosis and relapse-free survival in some tumour subtypes: ER-negative (p = 0.00033), HER2-positive (p = 0.004) and luminal B (p = 0.003) subtypes." (PMID 32418991, 2020). "Herein, the potential antitumor activities of a dual NUAK1/ULK1 inhibitor MRT68921 were evaluated in both tumor cell lines and animal models." (PMID 32873786, 2020). "A tumour-promoting role for NUAK1 is strengthened by studies where elevated NUAK1 correlates with poor prognosis in several malignancies, including EOC." (PMID 32429240, 2020). "While using xenograft tumour samples collected from our previous study, there was a significant decrease in NUAK1 protein expression in OVCAR8-STK11KO tumours as compared with OVCAR8 tumours." (PMID 32429240, 2020). "In contrast, upon NUAK1 inhibition in MYC-driven tumor cells termination is suppressed and RNAPII is trapped in a form that is not involved in productive transcription." (PMID 32006464, 2020). "NUAK1 has been found in many studies to act as the target of miRNAs in during the development of neoplasms." (PMID 29575772, 2019). "In normal diploid fibroblasts, NUAK1 is induced upon aging, mediating senescence, further supporting a tumor-suppressing function." (PMID 30622137, 2019). "Our data point to a novel role for calcium in supporting tumour cell viability and clarify the synthetic lethal interaction between NUAK1 and MYC." (PMID 29106388, 2018). "Previous work revealed a crucial role for NUAK1 in supporting viability of tumour cells specifically when MYC is overexpressed." (PMID 29106388, 2018). "Overall, miR-203 has a tumor-suppressing role in invasion and EMT induction by targeting NUAK1 in HNSCC, suggesting miR-203 as a potential new diagnostic and therapeutic target for the treatment of HNSCC." (PMID 26882562, 2016). "Elevated expression of NUAK1 leads to enhanced proliferation, invasion, and metastatic capabilities in diverse tumor cell types." (PMID 27833898, 2016). "NUAK1 (NUAK family SnF1-like kinase-1) and NUAK2 protein kinases are activated by the LKB1 tumour suppressor and have been implicated in regulating multiple processes such as cell survival, senescence, adhesion and polarity." (PMID 24785407, 2014). "A synthetic lethal siRNA screen also suggested that NUAK1 operates as an essential survival factor in oncogenic Myc-driven tumours and proposed that inhibitors of NUAK1 would have utility for treatment of such tumours." (PMID 24171924, 2014). "Here, we show that LKB1 tumor suppressor is a DNA damage sensor, and together with its downstream kinase NUAK1, contributes to UVB-induced CDKN1A degradation, allowing DNA repair and genomic integrity." (PMID 25329316, 2014). "Moreover, NUAK1 inhibition causes tumor ICD through H2O2/•OH accumulation and ER stress, as NRF2, downstream of NUAK1, suppresses antioxidant gene expression." (PMID 41162811, 2025). "Here, our study first provided novel insights into the role of NUAK1 on tumor immune evasion." (PMID 39901136, 2025). "However, the specific differentiation phenotype of CD8+ T cells induced by NUAK1 in the tumor microenvironment awaits investigation in our future work." (PMID 39901136, 2025). "Additionally, the results from the multiple immunofluorescence analysis of NUAK1, CD8α, and GZMB demonstrated that the overexpression of NUAK1 markedly decreased the population of GZMB+ CD8+ T cells within the tumor microenvironment." (PMID 39901136, 2025). "Through immunohistochemical (IHC) staining, we found that the tumor tissues with a higher expression of NUAK1 had a decreased CD8+ T cell infiltration, Pearson correlation analysis showed NUAK1 expression was negatively correlated with CD8+ T cell infiltration." (PMID 39901136, 2025).
tumor (continued). "Similarly, in subcutaneous xenograft tumor model, IHC staining suggested that overexpression of NUAK1 greatly promoted PD-L1 expression." (PMID 39901136, 2025). "Most of the current knowledge regarding NUAK1 is derived from the field of oncology, where NUAK1 is known as a tumor survival factor that, amongst other functions, is involved in mitochondrial ATP production and mitochondrial dynamics (i.e., fission and fusion)." (PMID 38892400, 2024). "Moreover, the elevated expression of NUAK1 positively correlated with tumor invasion depth, lymph node metastasis, pathological TNM stage, and poor survival in ESCC patients." (PMID 37919754, 2023). "In addition, the number of tumor cells invaded through Matrigel were decreased in both tested NUAK1-depleted ESCC cells." (PMID 37919754, 2023). "This may indicate that NUAK1-NF-κB crosstalk differs between tumours and spheroid or xenograft models of EOC, but may also reflect the possibility that NUAK1 mRNA expression is not a reliable surrogate for NUAK1 activity." (PMID 35194062, 2022). "Furthermore, NUAK1 not only is a key component of antioxidant defense systems but also is vital to tumor survival." (PMID 35872695, 2022). "Furthermore, we investigated the relationship between this model and TME, and the results indicated that CPEB1, NOTCH3, NUAK1, and PDPK1 were strongly associated with the expression of tumor checkpoints and tumor immune infiltration." (PMID 36072578, 2022). "Silencing NUAK1 increases the release of ROS and prevents tumor cell replication." (PMID 35872695, 2022). "Additionally, other microRNAs, like miR-204, were found to have negative correlation with the expression of NUAK1, and miR-204 can act as a tumor suppressor in NSCLC tumor invasion through the down-regulation of NUAK1." (PMID 33750398, 2021). "In addition, NUAK1 increases invasion in tumor cells mediated through MMP-2 and MMP-9 proteins and has been observed in NSCLC cells." (PMID 34685740, 2021). "A few miRNAs interacting with the NUAK1 network in different tumor types have been described." (PMID 34685740, 2021). "Multiple studies have provided evidence that NUAK1 can have tumour-promoting functions." (PMID 32429240, 2020). "Finally, NUAK1 loss in EOC cells extends xenograft host survival, and the resultant tumours also lack fibronectin." (PMID 32429240, 2020). "Thereby, NUAK1 cell location could be relevant for metabolic adaptation along with tumor progression." (PMID 32754444, 2020). "Accordingly, NUAK1 promoted cell survival and inhibited apoptosis; therefore, NUAK1's role in complete glucose oxidation by increased mitochondrial activity could also contribute to tumor viability." (PMID 32754444, 2020). "MiR‐96 suppressed tumour growth by targeting NUAK1 in pancreatic cancer." (PMID 29575772, 2019). "Restoration of miRNA-203 suppressed NUAK1, which decreased tumor invasion and LNM." (PMID 30901831, 2019). "Moreover, elevated NUAK1 levels can drive invasion of pancreatic cancer or exert tumor-promoting effects in breast cancer." (PMID 30622137, 2019). "Importantly, Ca2+-dependent activation of the AMPK–mTORC1 metabolic checkpoint requires both PKCα and NUAK1, and depletion of either drives pronounced apoptosis, suggesting a positive role for this pathway in tumour maintenance." (PMID 29106388, 2018). "Also, the LKB1-AMPK pathway, including NUAK1 has a prominent role in growth control and tumor suppression." (PMID 29963229, 2018). "Recent efforts have described small-molecule inhibitors targeting NUAK1/2 that have demonstrated in vitro efficacy against tumor cell proliferation and migratory potential, highlighting the possibility that NUAK1 may represent a therapeutic target." (PMID 27833898, 2016). "NUAK1 is known to possess tumor suppressive properties through the control of cellular senescence." (PMID 23818951, 2013).
tumor (continued). "Although other work suggests an attenuating role for NUAK1 in TGFβ signalling, concurrent signalling, cell lineage, and organ context are all likely to influence this activity, and NUAK1 may thus participate in the pathology of PDAC via both tumour cell‐intrinsic and stromal activities." (PMID 36975767, 2023). "Thus, our finding showed that NUAK1 knockdown inhibited the tumor growth and proliferation." (PMID 35872695, 2022). "In one experiment, it was found that NUAK1 was associated with decreased oxidative stress in tumors; thus, we hypothesized that increased expression of NUAK1 could potentially alleviate oxidative stress processes, reduce the production of reactive oxygen, and hinder tumor cell apoptosis." (PMID 35872695, 2022). "Finally, we confirmed the effect of NUAK1 expression on the growth of tumor by in vivo experiments." (PMID 35872695, 2022). "Therefore, ULK1 activity may contribute to the survival of tumor cells under the conditions of NUAK1 inhibition and oxidative stress." (PMID 32873786, 2020). "In the present study, we found that knockdown of β-catenin significantly blocked NUAK1-induced PD-L1 at transcriptional level in HCC cells, highlighting the significance of β-catenin in tumor immune escape." (PMID 39901136, 2025). "The levels of NUAK1 expression and the infiltration of CD8+ T cells were assessed in tumor tissues from HCC patients and mice xenograft model." (PMID 39901136, 2025). "In this study, we discovered that NUAK1 induces the expression of PD-L1 at the transcriptional level, thereby reducing the infiltration and activity of CD8+ T cells in tumor tissues." (PMID 39901136, 2025). "Conversely, the depletion of NUAK1 notably increased both the quantity and activity (GZMB+) of CD8+ T cells in the tumor." (PMID 39901136, 2025). "Collectively, these findings indicated that NUAK1 inhibits CD8+ T cell infiltration and activity in tumor microenvironment." (PMID 39901136, 2025). "The NUAK1 inhibitor induces endoplasmic reticulum stress through the inhibition of the NRF2 antioxidant pathway, thereby triggering ICD of tumor cells and the release of DAMPs; e.g., CRT and ATP, DC—mediated antigen presentation." (PMID 40877572, 2025). "IHC analyses of tumor tissues from HCC patients suggested that the levels of p-GSK3β and β-catenin were positively correlated with NUAK1 expression." (PMID 39901136, 2025). "ARK5 (NUAK1, NUAK family, SNF1-like kinase 1) is a tumor survival factor that is Akt-promoted during nutrient starvation and serves as an ATM kinase." (PMID 38282096, 2024). "Of the 16 kinases originally identified in the tumour dataset, 6 were also found to be differentially expressed in the cell line panel: AKT3, MYLK, PRKD1, AXL, NUAK1 and DCLK1." (PMID 33673003, 2021). "Clearly, these investigations point out the possibility of a major role of the NUAK1 and NUAK2 protein kinases in tumor development and support their potential role as novel therapeutic targets." (PMID 34685740, 2021). "In this manner, determining the regulatory network that involves NUAK1 and NUAK2 in tumor development is important." (PMID 34685740, 2021). "As cytotoxic therapy induces elevated ROS levels and triggers the ULK1 pathway to activate protective autophagy and mitophagy, dual targeting of NUAK1 and ULK1 by MRT68921 can be beneficial in tumour management." (PMID 34706732, 2021). "Despite recently accumulated evidence, only limited data are available regarding NUAK1 and NUAK2 and their role in cellular physiology, their potential downstream targets in various tissues, and how gene amplifications affect tumor development." (PMID 34685740, 2021).